CXCR4 (C-X-C motif chemokine receptor 4)
Diseases named in the same sentence as CXCR4 in open-access papers (continued):
Sharing a sentence is not in itself a finding about the gene and the disease.
tumor (continued). "In addition, tumor volumes directly correlated with CXCR4 expression supporting a role for CXCR4 in growth promotion." (PMID 27528222, 2016). "In comparison to [18F]FDG (44 lesions), CXCR4-directed PET visualized 33 tumor manifestations." (PMID 26843617, 2016). "In our present paper, the serum concentrations of CXCL12 were significantly higher, while CXCR4 was significantly lower in EC patients compared to healthy controls, while the levels of classical tumor markers as well as CRP were found to be also higher in EC patients than in control group." (PMID 27041792, 2016). "In the long-run, steady CXCL12 binding causes CXCR4 desensitization resulting in a resting, non-deploying state of hematopoietic stem cells and tumor cells, likewise." (PMID 27462860, 2016). "Accordingly, SDF-1/CXCR-4 inhibition prevents macrophage infiltration and tumor regrowth after RT." (PMID 27064581, 2016). "We selected samples where CXCR4 RNA levels are high (Log2 ratio > 2) i.e., tumor cells which might be dependent on CXCR4 signaling, and divided those patients into GNG4 high (RNA Log2 ratio > −0.79) and GNG4 low (RNA Log2 ratio < −0.79) groups." (PMID 27382437, 2016). "Further analysis of cancer samples in different disease stages showed that some GPCRs, such as endothelin receptor A, may be involved in early tumor progression while other GPCRs, such as CXCR4, are critical for tumor invasion and metastasis." (PMID 27379162, 2016). "As we previously found that ECFCs home to tumor site by exploiting the CXCR4/SDF1 axis, we determined whether the presence of ChAumix was able to alter CXCR4 expression." (PMID 27223433, 2016). "Thus, tumor stroma-directed therapies targeting CXCR4 axis that mediates this crosstalk within tumor microenvironment have recently attracted increased attention from researchers." (PMID 27556298, 2016). "CXCL12 regulates tumor growth, angiogenesis and progression by acting on CXCR4-expressing cells." (PMID 27590504, 2016). "Tumor hypoxia could increase CXCR4 expression evident by high accumulation of 89Zr-CXCR4-mAb in the center of H1155 tumors." (PMID 26848769, 2016). "Other researchers have also showed that blocking the interaction between SDF-1 and CXCR4 could inhibit the number or size of tumor metastases." (PMID 26851944, 2016). "The serum concentrations of CXCL12 and CXCR4 and classical tumor markers such as carcinoembryonal antigen (CEA) and squamous cell cancer antigen (SCC-Ag) were measured using immunoenzyme assays, while C-reactive protein (CRP) levels were assessed by immunoturbidimetric method." (PMID 27041792, 2016). "CXCR4 was additionally shown to be involved in early stage GC development through recruitment of stromal cells and establishment of progenitor niche to favor tumor growth." (PMID 27007162, 2016). "Moreover, the relationship between serum concentrations of CXCL12/CXCR4 and clinicopathological parameters of tumor as well as the EC patients' survival was presented." (PMID 27041792, 2016). "CXCR4 overexpression contributes to tumor growth, progression and metastasis." (PMID 26848769, 2016). "Moreover, the Lgr5+/CXCR4+ cells generated significantly more tumor spheres than CXCR4+/Lgr5- and Lgr5+/CXCR4- cells." (PMID 27835894, 2016). "To examine whether B cell-mediated 4T1 tumor cell death involves both Fas/FasL and CXCR4/CXCL12 pathways, we added anti-FasL and AMD3100 in the same experiment." (PMID 27528023, 2016). "In conclusion, the zebrafish xenotransplantation model, in which inter-species crosstalk is maintained, has provided new insight into the metastatic events associated with TNBC and into the employment of a potential compound to limit CXCR4-dependent tumor early metastases." (PMID 26744352, 2016). "Moreover, in addition to p85β (PIK3R2) and Sox2, IRS1, VEGF and CXCR4 have been reported to be target genes of miR-126-3p and to participate in miR-126-3p-induced tumor suppression." (PMID 27191494, 2016).
tumor (continued). "In all patients imaging results could be compared to immunohistological staining for SSTR2a/5 and CXCR4 derived from biopsies of the primary tumor (n = 6) or metastases (n = 4)." (PMID 26843617, 2016). "Importantly, we demonstrate that cross-communication between the zebrafish and human ligands and receptors takes place and human tumor cells expressing CXCR4 initiate early metastatic events by sensing zebrafish cognate ligands at the metastatic site." (PMID 26744352, 2016). "Plerixafor, a competitive CXCR4 inhibitor and a stem cell mobilizer, is effective in inhibiting initial establishment of tumor cells into the bone microenvironment, whereas the same drug is ineffective in containing the expansion of pre-existing bone metastasis." (PMID 27809841, 2016). "Therefore, considering the level of conservation, we verify that the CXCR4 signaling on human tumor cells is activated by both zebrafish Cxcl12 ligands." (PMID 26744352, 2016). "In summary, nitration on Tyr7 under inflammatory conditions is a novel natural posttranslational regulatory mechanism of CXCL12 which may downregulate the CXCR4-mediated inflammatory and tumor-promoting activities of CXCL12." (PMID 27566567, 2016). "CXCR4 was located diffusely in the cytoplasm and nucleus of tumour cells." (PMID 26404566, 2015). "For example, in the paired cell lines SW480 and SW620, which are derived from the same patient at different stages of CRC, SW480 cells (from the primary tumour) showed a more robust elevation of CD26 while SW620 cells (from a later metastasis) showed the more dramatic change in CXCR4." (PMID 26552750, 2015). "In addition, the stroma cells from specialized microenvironments actually modulate CXCR4 expression, which is responsible for tumorigenesis and tumor progression." (PMID 25669980, 2015). "Since CXCR4 has been shown to play a role in tumor metastasis by promoting cell migration and invasion we investigated whether the attenuation of CXCR4 expression by IL-24 had a consequential biological effect." (PMID 25775124, 2015). "Additionally, we were able to demonstrate a further increase within the G3 group, from G3a to G3b neoplasms, and found a significant correlation between Ki-67 and CXCR4 expression." (PMID 26259237, 2015). "The CXCL12 and CXCR4 axis is involved in tumor progression, angiogenesis, metastasis, and survival." (PMID 26176534, 2015). "CXCR4 was described as the most frequently expressed chemokine receptor on tumor cells." (PMID 25955316, 2015). "Activation of SDF-1/CXCR4 signaling is a key characteristic of metastatic tumor cells." (PMID 26517240, 2015). "In this way, CXCR4-related stemness properties displayed by tumor cells with metastatic capacity could be potentially exploited for therapeutic targeting of CSC using treatment anti-CXCR4 (e.g. TN14003 or AMD3100), also avoiding the effects of their exosomes." (PMID 26528758, 2015). "Preclinical studies suggest CXCR4 antagonists may enhance anti-tumor activity by blocking interactions with stromal cells mediating immune protection and tumor survival." (PMID 25941795, 2015). "The anti-tumor effect of AMD3100 (anti-CXCR4) was tested in GBM explants." (PMID 25860928, 2015). "Thus, CXCR4 expression is involved in exosomes-gene expression profile changes related to biological process enrichment found in tumor cells with high stemness potential." (PMID 26528758, 2015). "Furthermore, miR-222 inhibited the recruitment of macrophages by targeting CXCL12 and inhibiting CXCR4 to suppress 4T1 tumor growth." (PMID 26689540, 2015). "Moreover, CXCR4-expressing tumor cells migrate along the CXCL12 gradient derived from nerves, eventually leading to metastatic spread along the alternative route establishing PNI." (PMID 25605248, 2015). "Consequently, this observation implies that CXCR4-expressing tumor cells are directed along a cytokine gradient to CXCL12-expressing organs to form metastasis." (PMID 26091099, 2015).
tumor (continued). "Moreover, we call attention to the importance of CXCL12-γ within the tumor environment, as its high ligand binding properties elicits higher CXCR4+ migration and requires interventions such as co-inhibition of CXCR4 and CXCR7 to significantly reduce migration." (PMID 25909600, 2015). "We found that CSC-derived EVs promoted persistent phenotypical changes in MSCs characterized by an increased expression of genes associated with cell migration (CXCR4, CXCR7), matrix remodeling (COL4A3), angiogenesis and tumor growth (IL-8, Osteopontin and Myeloperoxidase)." (PMID 25797265, 2015). "In support of this notion, it was demonstrated that of CXCR4 may play a critical role as a chemoattractant in cancer development possibly at the level of the tumor niche." (PMID 25669980, 2015). "Further studies should evaluate whether CXCR4-targeted therapy in combination with cytotoxic agents enhances the anti-tumor effects of chemotherapy in human clinical trials." (PMID 25544759, 2015). "In addition, previous studies investigating the expression of CXCR4 in different tumor entities by immunohistochemistry (IHC) often yielded only cytoplasmic or nuclear staining of this membrane-bound receptor." (PMID 25671300, 2015). "Furthermore, we demonstrated that the SDF-1/CXCR4 axis plays an important role in mediating the tumor-promoting effect." (PMID 25890096, 2015). "It is important to explore new drugs that target CXCR4 or interrupt SDF-1α/CXCR4 complex which could have a profound impact as a therapeutic agent to suppress tumor progression." (PMID 26318034, 2015). "However, an apparent theme is the contrast between cellular CXCR4 localization through immunohistochemical staining in tumor cell lines and breast tissue and the correlation with a more aggressive clinical outcome." (PMID 26161302, 2015). "Chemokine receptor 4 (CXCR4) is a seven-transmembrane G protein-coupled chemokine receptor and it is the chemokine receptor most commonly expressed in tumor cells, with increased expression in presence of metastatic disease in many tumors including bone and soft tissue sarcomas." (PMID 25613038, 2015). "As CXCR4 is expressed in cells in multiple organs including lymph nodes, lungs, and liver, epithelial tumor cells may take advantage of the principle of homing mechanisms to direct the metastasis of CXCL12-positive tumor cells to CXCR4 positive organs." (PMID 25806371, 2015). "In summary, our study results demonstrate IL-24 disrupts the SDF-1/CXCR4 signaling pathway resulting in reduced cell migration and invasion and combination therapy of IL-24 with pharmacologic or genetic CXCR4 inhibitor produced a greater inhibitory activity on tumor cell migration." (PMID 25775124, 2015). "CXCR4 is widely expressed in different malignant tumor entities." (PMID 25671300, 2015). "Slight Pim-dependent increases were observed in the proportion of mitotic cells and in the areas of lymphatic vessels, while more significant upregulation was detected in the formation of tumor vasculature and in the phosphorylation and cell surface expression of CXCR4." (PMID 26075720, 2015). "No obvious association was observed between CXCL12 expression and lymph node metastasis, suggesting that CXCL12 chemotaxis may only be related to CXCR4 expression on the tumor cell membrane." (PMID 25866764, 2015). "Notably, all five tumor-bearing mice after inoculation of CXCR4+ small cells had multiple tumor nodules (Fig 3Bii), and began to develop bloody ascites within 3 weeks (Fig 3Biii)." (PMID 26110809, 2015). "Also, CXCR4 correlates with the histological grade and invasive capacity of tumor cells, as well as with tumor cell survival." (PMID 25852766, 2015).
tumor (continued). "Interestingly, collagen type I and CXCR4 were predominantly co-localized, and the number of double-positive cells was significantly increased in the bevacizumab-resistant tumours." (PMID 26635184, 2015). "Here, we found C-X-C chemokine receptor type 4 (CXCR4) can be a marker for PD-associated gastric CSCs and demonstrated that TGF-β enhances the efficacy of anti-tumor drugs via induction of cell differentiation /asymmetric cell division in the CXCR4+ CSC population even in a dormant state." (PMID 26110809, 2015). "The IRS of the CXCR4 staining differed significantly among the three tumor entities." (PMID 25671300, 2015). "Notwithstanding the CXCR4 involvement in chemotaxis process, CXCR4 can drive epithelial to mesenchymal transition along with an upregulation of other chemokine receptors and cytokines, leading to cell migration, lymphatic invasion, and tumor metastasis." (PMID 26161302, 2015). "Furthermore, CXCR4 is involved in various aspects of cancers, such as metastasis, tumor growth, cell cycle progression, and drug resistance." (PMID 26083776, 2015). "Tumor-promoting factors (CXCR4, MMP-9, NF-κB) were significantly increased in the proliferating and invasive compared to the adherent cells, however HCT116R cells overexpressed factors in comparison to the parental HCT116, suggesting an increase in malignancy behavior." (PMID 25884903, 2015). "To further elucidate the effect of CXCR4 on TPD7’s cell invasion inhibition, we evaluated the effect on cell migration and invasion between wild tumour cells and CXCR4 knockdown cells, we observed the inhibition on cell mobility by wound healing assay and cell invasion by Millicell system." (PMID 25753200, 2015). "Our study not only indicates a pathogenesis for PCa PNI, but also provides evidence that CXCL12/CXCR4 axis might be a novel therapeutic target to prevent tumor perineural dissemination in PCa." (PMID 25605248, 2015). "Moreover, poly I:C treatment significantly increased PSA expression in tumour cell and massively reduced anti-CXCR4 staining." (PMID 25444175, 2015). "Furthermore, inhibition of CXCR4 by AMD3100 mobilizes tumor cells out of the BM and leads to increased chemosensitivity, although the effect of this treatment on the cell cycle remains to be determined." (PMID 25504440, 2015). "Conversely, SK-Hep1 cells with CXCR4 knockdown generated smaller tumours than control cells." (PMID 26404566, 2015). "Indeed, CXCR4 is overexpressed in more than 20 different tumor histotypes and its involvement in metastasis was broadly demonstrated." (PMID 26062132, 2015). "However, our results showed that negligible level of CXCR4 was detected on 4T1 cells but high level of CXCR4 was found from the primary culture of 4T1 tumours in vivo." (PMID 26592552, 2015). "The chemokine receptor CXCR4 is expressed in more than 23 different tumor types." (PMID 26259237, 2015). "After 6 weeks of the transplantation, the xenotransplanted cancer cells originally obtained from both the orthotopic tumor and the lung repopulated the cells with a high expression level of CXCR4 in the orthotopic tumor and the cells with a low expression level of CXCR4 in the lung metastasis." (PMID 26083776, 2015). "Moreover, inoculation of CXCR4-cell-derived exosomes in immunocompromised mice stimulated primary tumor growth and metastatic potential." (PMID 26528758, 2015). "Indeed, silencing CD133-CXCR4 markers prevented metastasis of PDAC tumor in xenografts, leading Hermann and colleagues to proposing the CXCR4 as a target, along with CD133, to prevent metastasis." (PMID 26244163, 2015). "CXCR4-positive tumor cells migrate toward distant organs in response to a CXCL12 gradient." (PMID 25605248, 2015). "However, the level of cytoplasmic and nuclear CXCR4 expressions was significantly higher in tumour than peritumour tissues." (PMID 26404566, 2015).
tumor (continued). "Also, anti-CCL20 neutralizing antibodies inhibited the growth of prostate cancer cells that overexpress CXCR4 in a tumour xenograft model." (PMID 26062132, 2015). "We next investigated whether IL-24 could inhibit SDF-1-induced tumor cell migration and suppress the CXCR4 signaling pathway." (PMID 25775124, 2015). "Indeed, CXCR4 is widely expressed on tumor cells, and the preferential sites of metastases, such as bone, liver, and lung, express high levels of its ligand, CXCL12." (PMID 25897429, 2015). "However, only in T-ALL anti-CXCR4 monotherapy shows strong efficacy, suggesting a strong dependence of these tumor cells on CXCR4 signaling." (PMID 26682242, 2015). "The SDF-1α-CXCR4 interaction promotes tumour progression by several possible mechanisms." (PMID 25753200, 2015). "However, no statistical differences were found between clinicopathological factors (age, gender and tumor size) and NF-kB-p65, CXCR4 expression." (PMID 25503960, 2015). "CXCR4 promotes tumour progression by direct and indirect mechanisms." (PMID 25598217, 2015). "Hypoxia in the tumor microenvironment and NF-κB have been indicated in CXCR4 overexpression." (PMID 25503960, 2015). "In addition, tumor-originated MIF leads to enhanced accumulation of interleukin-17-producing subsets of tumor-infiltrating lymphocytes by binding to CXCR4, which can affect patient prognosis." (PMID 26347749, 2015). "In the current study, decreasing IFN-γ prompted CXCR4 expression on cancer cells, which could help tumor cells escape from immunity." (PMID 25609202, 2015). "Thus, the alteration in the EZH2/miR-622/CXCR4 pathway contributes to tumour development and represents therapeutic targets." (PMID 26404566, 2015). "The enhancement of tumor cell invasion is effectively countered by CXCR4 shRNA." (PMID 25605248, 2015). "The presence of the SDF-1/CXCR4 system on these cells suggests that endogenous bone marrow-derived cells may also migrate to tumor sites and contribute to the formation of tumor stromal tissue in vivo." (PMID 24792410, 2015). "siRNA mediated knockdown of CXCR4 reduced tumor cell migration against SDF-1 gradient (P<0.05)." (PMID 25775124, 2015). "Hence, CXCR4 is postulated to be involved in tumor progression, metastasis, adaptation to hypoxia, and stem cell survival." (PMID 25671300, 2015). "An in-depth research for the role of CXCR7, especially regarding the mechanisms that alter overall availability, distribution and gradients of CXCL12 in tumor microenvironments to regulate the invasion and metastasis of CXCR4 expressing cells, is imperative in the future." (PMID 25605248, 2015). "Additionally, μPET imaging with Pentixafor detected xenografted MM tumors with high specificity and contrast, and tracer accumulation was found to correlate with CXCR4 cell surface expression in tumor tissue." (PMID 25736399, 2015). "Comparison of phospho-CXCR4 signals to the average CXCR4 signals in each tumor revealed that both Pim-1 and Pim-3 had significantly increased the relative amounts of phospho-CXCR4, while Pim inhibition by DHPCC-9 had decreased it even below the level observed in the mock-transfected samples." (PMID 26075720, 2015). "Because CXCL12 is the target molecule of HIF-1α, the hypoxic condition resulting from bevacizumab treatment could lead the tumour cells to produce CXCL12, which would in turn prompt the CXCR4+ cells to migrate into the tumour." (PMID 26635184, 2015). "CXCR4 was predominantly localized at the plasma membrane of the tumor cells." (PMID 25671300, 2015). "In addition, CXCR4 gene signatures also included upregulated survival genes and downregulated pro-apoptosis genes in CXCR4+ tumor cells." (PMID 25704881, 2015). "CXCR4 expression is required for tumor initiation and progression." (PMID 26318034, 2015). "Our pseudo-tumor simulations demonstrate that blocking both CXCR4 and CXCR7 receptors may be a potential method to inhibit migration in such gradients." (PMID 25909600, 2015).